TRPV6 (transient receptor potential cation channel subfamily V member 6)
Diseases named in the same sentence as TRPV6 in open-access papers (continued):
Sharing a sentence is not in itself a finding about the gene and the disease.
prostate carcinoma (continued). "In prostate cancer, TCAF1 negatively regulates cell migration when bound to TRPM8, but TCAFs are partner proteins for other ion channels, including TRPV6." (PMID 36012311, 2022). "For instance, TRPV2, TRPV6, and TRPM8 were differentially expressed between normal prostate and prostate carcinomas." (PMID 27023518, 2016). "Since nuclear factor of activated T-cells (NFAT) was recently reported to confer promitogenic role of TRPV6 in prostate cancer cells, we also studied NFAT expression relationship between TRPV6 and NFAT activity in NET cells." (PMID 27450545, 2016). "TRPV6 calcium channel is a prospective target in prostate cancer (PCa) since it is not expressed in healthy prostate while its expression increases during cancer progression." (PMID 38879621, 2024). "The most important thing is that in prostate cancer (PCa) TRPV6 channel is absent in healthy prostate while its expression appears de novo and correlates with the prostate malignancy, making it a prospective therapeutic target for the treatment of PCa." (PMID 38879621, 2024). "In prostate cancer, an interaction between SOCE and TRPV6 was already described and could in principle occur in PDAC as well." (PMID 38136316, 2023). "Using prostate cancer resection specimens, we have confirmed the absence of the TRPV6 protein in both healthy and benign hyperplasia and its expression and correlation to the prostate cancer grades using Northern blot and PCR." (PMID 36613866, 2022). "Though TRPV6 was proposed as a prognostic marker for advanced prostate cancer in the early 2000s, no reliable tool to detect TRPV6 channels in clinics has been reported or used for diagnostic purposes so far." (PMID 36613866, 2022). "Using prostate cancer resection specimens, we have confirmed the absence of the TRPV6 protein in both healthy and benign hyperplasia, as well as its expression and correlation to the prostate cancer grades." (PMID 36613866, 2022). "Considering the important role that TRPV6 and CaSR have in cancer, we undertook these pilot experiments to investigate the MEMRI response in different types of breast and prostate cancer animal models, characterized by different level of expression of these molecules." (PMID 32931488, 2020). "Finally, the pharmacological targeting of TRPV6 by the peptide SOR-C13 led to the inhibition of cell growth in cellular and animal models for ovarian and prostate cancers." (PMID 33171939, 2020). "Manganese contrast enhancement in breast or prostate cancer animal models well correlated with CaSR expression (p<0.01), whereas TRPV6 expression levels appeared not relevant to the Mn uptake." (PMID 32931488, 2020). "The transient receptor potential cation channel subfamily V member 6 protein (TRPV6), is a calcium selective cation channel that plays a critical role in calcium uptake in epithelial tissues in epididymis, placenta, and prostate cancer." (PMID 31683902, 2019). "Elevated TRPV6 and the resulting sustained elevation of intracellular calcium acts through downstream activation of Nuclear Factor of Activated T-cell signalling system (NFAT; a transcription factor) in prostate cancer." (PMID 28150073, 2017). "The activation of partner gene TRPV6 was reported to be critical to NFAT in prostate cancer cells." (PMID 25418933, 2014). "In this study, we measured the expression of the L-type and T-type voltage-gated calcium channels, the nonselective cation channels TRPM-6 and TRPM-7, and the selective calcium channel TRPV-6 in nontumorigenic prostate cells and hormone-dependent and hormone-resistant prostate cancer cells." (PMID 38131032, 2023). "Finally, our work demonstrates the use of the rabbit polyclonal antibodies, which are by their virtue transiently activating antibodies and have a very high if not absolute efficiency against prostate cancer cells expressing TRPV6 on the plasma membrane." (PMID 36980711, 2023).
prostate carcinoma (continued). "Moreover, TRPV6 is strongly expressed in advanced prostate cancer, with little or no expression in healthy and benign prostate tissues, and high TRPC6 expression has been documented in esophageal squamous cell carcinoma." (PMID 33076385, 2020). "Since we have already demonstrated the role of TRPV6 channel in proliferation of prostate cancer cells, and knowing that there is no chemical compound available so far to selectively block TRPV6, we used siRNA approach to selectively knockdown TRPV6." (PMID 21347289, 2011). "However, the allele frequencies between these groups are similar indicating that onset of prostate cancer is independent of the TRPV6 genotype." (PMID 19857260, 2009). "We show that the TRPV6 genotype is not correlated with the onset of prostate cancer." (PMID 19857260, 2009).
breast carcinoma (46 papers, 2012 to 2025). "TRPV6 channels are significantly expressed in breast cancer cells and are associated with malignancy and prognosis." (PMID 40078961, 2025). "In the breast cancer cell line T-47D, tamoxifen, an estrogen receptor antagonist, caused TRPV6 mRNA to be downregulated, whereas progesterone and estradiol elevated it." (PMID 38534438, 2024). "Using MDA-MB-231 and MCF-7 human breast cancer cell lines we demonstrated the oncogenicity of WT TRPV6 and GOF mutant R532Q predicted to be pathogenic." (PMID 34413465, 2021). "We also analyzed the expression of TRPV6 in ER− breast cancer patients and found that the high TRPV6 level is associated with poor overall survival (HR = 1.92, 1.25–3.04; p = 0.0042) and relapse-free survival (HR = 1.31, 1.04–1.64; p = 0.019)." (PMID 34413465, 2021). "The fact that the molecular mechanism underlying the function and regulation of TRPV6 is still not well understood hampers, in particular, the understanding of how TRPV6 contributes to breast cancer development." (PMID 34413465, 2021). "In at least prostate and breast cancer, high TRPV6 expression is linked to cellular proliferation and invasion through Ca2+-dependent pathways and its high levels have been proposed to act as a prognostic factor." (PMID 34356643, 2021). "Malfunction due to genetic mutations in or altered expression of TRPV6 has been clinically linked to human breast cancer and several other diseases." (PMID 34413465, 2021). "Upregulation of TRPV6 Ca2+-channel has been associated with a number of human malignancies and its high expression in breast cancer has been linked to both proliferation and invasive disease." (PMID 32895467, 2020). "In prostate and breast cancer, TRPV6 is substantially associated with highly proliferative and metastatic tumours." (PMID 32931488, 2020). "TRPV6 channel-mediated Ca2+ influx is involved in cell proliferation, which may be associated with breast cancer cell migration." (PMID 35573736, 2022). "Multiple zinc transporters (such as ZnT2, ZIP6/LIV1, ZIP7 and ZIP10), zinc-permeable ion channels (such as TRPC6, TRPM7, and TRPV6), as well as metallothionein were reported to be overexpressed in breast cancer, some of which are associated with breast cancer metastases and poor prognosis." (PMID 34627839, 2021). "Additionally, we show that TRPV6 levels tightly correlate with the expression of epithelial mesenchymal transition (EMT)-linked factors and depletion of TRPV6 from mammary epithelial or breast carcinoma cell lines leads to downregulation of several EMT-associated proteins." (PMID 32895467, 2020). "Overexpression of TRPV6 in breast cancer is a common event, with 93.3% of biopsies showing higher levels of the protein than non-invasive tumour areas, particularly in invasive areas." (PMID 40078961, 2025). "Inhibiting TRPV6 channels reduces the proliferative capacity of breast cancer cells and enhances their sensitivity to chemotherapeutic agents." (PMID 40078961, 2025). "TRPV6 is upregulated in metastatic breast cancer, and its overexpression or upregulation accelerates the migration of the primary breast cancer cells." (PMID 38534438, 2024). "The activity of TRPV6 in breast cancer cells is suppressed by Numb through electrostatic contact, which controls the influx of Ca2+." (PMID 38534438, 2024). "Different nuclear factors of activated T cells (NFAT) are activated in prostate and breast cancer cells by TRPV6 activity and the cytosolic calcium levels that follow." (PMID 38534438, 2024). "TRPV6 overexpression increases the basal intracellular levels of Ca2+ in breast cancer cells, and positively regulates the expression of regulator gene through CaM/Calcineurin/NFAT pathway, which regulates proliferation and apoptosis." (PMID 38706904, 2024). "TRPC1 has been implicated in breast cancer cell proliferation, whereas TRPC6, TRPM7, and TRPV6 have demonstrated their involvement in the regulation of breast cancer cell proliferation and migration." (PMID 39334351, 2024).
breast carcinoma (continued). "TRPV6 has a strong effect on the proliferation of breast cancer cells, which are regulated by estrogen, progesterone, tamoxifen, and 1, 25-vitamin D3." (PMID 38534438, 2024). "The expression of the TRPV6 gene is remarkably upregulated in several human malignancies, including the most common cancers: prostate and breast cancer." (PMID 37892239, 2023). "TRPV6 appears to be expressed in various cancer cell lines, but a direct identification of the TRPV6 protein using mass spectrometry has only been shown in the human breast cancer cell line, T47D, and in the human lymph node prostate cancer cell line, LNCaP." (PMID 37892239, 2023). "TRPV6 is a highly Ca2+ selective and constitutively active ion channel, highly expressed in malignancies including breast cancer." (PMID 35163823, 2022). "Clinical trials are ongoing with a novel TRPV6 inhibitor, in conjunction with standard-of-care therapy, for multiple subtypes of breast cancer, since some current treatments, such as tamoxifen, have been shown to negatively affect the TRPV6 channel as well." (PMID 34572386, 2021). "Increased levels of TRPV6 resulted in upregulation of EMT markers, possibly explaining the earlier findings on high TRPV6 levels in the invasive regions of mammary carcinomas." (PMID 34356643, 2021). "Further evidence of this, involving a calcium channel known as TRPV6, which is found to be overexpressed in breast cancer, along with many other cancers, has been found in clinical settings." (PMID 34572386, 2021). "We then utilized Ca imaging to the cell lines to determine the effect of the TRPV6 channel function on breast cancer cell growth." (PMID 34413465, 2021). "It was previously reported that patients with ER− breast cancer have higher TRPV6 mRNA expression than ER+ patients." (PMID 34413465, 2021). "It discussed significance of these gained mechanistic insights into TRPV6 gating and TRPV6-dependent human breast cancer progression to therapeutic interventions." (PMID 34413465, 2021). "In vitro analysis showed that TRPV6-silencing reduced breast cancer cell proliferation and promoted apoptosis." (PMID 36046118, 2021). "It is worth mentioning that calcitriol (100 nM) also up-regulates the expression of TRPV6 in T47D breast cancer cells." (PMID 32210800, 2020). "A number of TRPV6 inhibitors have already shown potential in reducing cell growth f.i. in breast cancer models." (PMID 32895467, 2020). "The transient receptor potential cation channel subfamily V member 6 (TRPV6), a representative calcium influx channel, is a channel associated with the progression of various cancers including prostate and breast cancers." (PMID 32033337, 2020). "The mechanisms behind this phenomenon are, however, poorly understood: TRPV6 gene amplification is responsible for only under 1% of the breast carcinoma cases with high TRPV6 expression." (PMID 32895467, 2020). "TRPV4 is downregulated in prostate, skin, and breast cancers, while TRPV6 is boosted in various tumors, including prostate and breast cancers." (PMID 33171939, 2020). "In breast carcinomas, overexpression of TRPV6 is a common event and the levels of this protein have been shown to be highly elevated, especially in the invasive regions." (PMID 32895467, 2020). "However, in prostate or breast cancer, TRPV6 is definitively associated with highly proliferative and metastatic tumours thus, the combination of both highly expressed calcium receptors may have affected the different timing of tumour development and progression that we observed." (PMID 32931488, 2020). "TRPV6 expression has been reported to be enhanced in ER- and HER2-positive breast cancer cells and is associated to cell migration and invasion in MDA-MB-231 cells." (PMID 30223530, 2018). "In breast cancer, TRPV6 expression is higher in invasive areas of breast cancer tissues in comparison to the corresponding non-invasive areas." (PMID 29772843, 2018).
breast carcinoma (continued). "The genes PRSS1, TRPV5 and PIP have so far been implicated in a few cancer types (pancreatic-, non-small cell lung- and breast cancer), while EphB6 and TRPV6 have been studied in relation to numerous cancer types." (PMID 29299148, 2017). "Reduction of TRPV6 expression by silencing RNA results in decreased cell proliferation and increased apoptosis in prostate and breast cancer cell lines." (PMID 28150073, 2017). "On the other hand, the expression of TRPV6 is up-regulated in time-dependent manner by estradiol and progesterone in breast cancer cell line." (PMID 26818094, 2016). "Later studies showed that TRPV6 is overexpressed in prostate and breast cancer cells, where it was relevant at stimulating calcium-dependently cancer cell proliferation and survival." (PMID 27450545, 2016). "Patients with high expression of TRPV6 exhibits a worse survival when compared to those with low or intermediate TRPV6 expression in breast cancer." (PMID 26818094, 2016). "There are also several genes close to this region that are associated with many types of cancer including breast cancer, EPH receptor B6 (EPHB) and Transient receptor potential vanilloid 6 (TRPV6)." (PMID 25423363, 2014). "TRPC1, TRPM7 and TRPM8 expression strongly correlated with proliferative parameters, and TRPV6 was mainly overexpressed in invasive breast cancer cells." (PMID 22692672, 2012). "Enhanced expression of the TRPV6 calcium channel is associated with unfavorable outcomes in breast cancer due to its promotion of invasion and metastasis, indicating that targeting TRPV6 could be a promising strategy for breast cancer treatment." (PMID 40078961, 2025). "Furthermore, in breast cancer cell lines with increased endogenous TRPV6 expression, silencing TRPV6 expression resulted in decreased basal calcium inflow and cell proliferation, along with decreased DNA synthesis." (PMID 38534438, 2024). "Still, silencing of TRPV6 channels resulted in reduced migration and invasiveness of the human-derived triple-negative MDA-MB-231 cells in-vitro and in increased apoptotic cell population in T47D breast cancer cells culture, similarly to what happens when exposed to TRPV6 inhibitor SOR-C13." (PMID 35163823, 2022). "The over-expression of TRPV6 mRNA has been reported in breast cancer." (PMID 35174089, 2022). "We showed that TRPV6 may play a role in the promotion of cancer development in breast cancer and lung adenocarcinoma, and lapatinib is negatively correlated with the expression of most TRPV molecules." (PMID 35174089, 2022). "TRPV6 is expressed in normal breast and breast cancer cell lines." (PMID 35573736, 2022). "For all breast cancer types, our analysis showed significant inverse correlation of the TRPV6 mRNA level with the overall survival rate (HR = 1.58, 1.25–1.99; p = 8.8e-05) and the relapse-free survival rate (HR = 1.45, 1.29–1.63; p = 6.9e-10), with a 95% confidence interval." (PMID 34413465, 2021). "The mechanism of how TRPV6 promotes breast cancer progression has yet to be determined." (PMID 34413465, 2021). "Finally, the Orai3 protein works in conjunction with TRPV6 to promote proliferation in prostate and breast cancer." (PMID 36046118, 2021). "Thus, these significant inverse correlations between the TRPV6 expression and survival rates found in all and ER− breast cancer patients nicely supported our data obtained using in vitro systems." (PMID 34413465, 2021). "In summary, the involvement of a PI3K/Akt/GSK-3β pathway and TRPV6/p85 interaction in breast cancer cell progression revealed in the present study not only confirms the previously reported role of Ca, but more importantly, provides a mechanistic understanding of the disease development." (PMID 34413465, 2021). "Indeed, aberrant TRPV6 expression has been detected in several cancer types, including breast cancer and pancreatic cancer." (PMID 34360952, 2021).